KEAP1 (kelch like ECH associated protein 1)
Diseases named in the same sentence as KEAP1 in open-access papers (continued):
Sharing a sentence is not in itself a finding about the gene and the disease.
breast cancer (81 papers, 2010 to 2026). A primary or metastatic malignant neoplasm involving the breast. "Previous studies performed by our research team indicate that the metabolic imbalances due nuclear factor Erythroid 2-related Factor 2 (NRF2) and Kelch-Like ECH Associated Protein 1 (KEAP1) lead to poor outcomes in breast cancer patients." (PMID 39001473, 2024). "The minor A allele of Keap1 rs11085735 has been associated with lower Keap1 and higher nuclear Nrf2 expression and decreased overall survival in breast cancer patients treated with radiotherapy and tamoxifen." (PMID 34861061, 2022). "For HER2-enriched subtype, KEAP1 was significantly associated with breast cancer grade and lymph node metastasis (all p < 0.05)." (PMID 35154262, 2021). "In a later study from the same group, it was consistently demonstrated that genetic polymorphisms in KEAP1 also affect the breast cancer risk and clinical outcome, modifying the effects of radiotherapy and tamoxifen treatments on patient survival." (PMID 33805996, 2021). "Higher nuclear Keap1 expression in postoperative samples was associated with the presence of bilateral breast cancer (p = 0.026)." (PMID 29348788, 2017). "KEAP1 gene hypermethylation in malignant gliomas, breast cancers, and colorectal cancers is associated with loss of function." (PMID 26247201, 2015). "However, Keap1 mutations have also been reported in other human cancers, for example, ovary (19%), gastric (11%), liver (9%), colon (8%), prostate (8%), and breast cancer (2%)." (PMID 35773670, 2022). "However, the MnP-driven oxidation of cysteine (Cys288) of the regulatory protein, Kelch-like ECH-associated protein 1 (Keap1) was demonstrated by redox proteomics of 4T1 breast cancer cells treated with MnTE-2-PyP5+/ascorbate." (PMID 34829640, 2021). "Furthermore, an N-terminal domain mutation of Keap-1 (C23Y) was identified in human breast cancer." (PMID 20932318, 2010). "Researchers demonstrated that miR-200a silencing was observed in breast cancer cells, and re-expression of miR-200a targeted the Keap1 3′-UTR, leading to Keap1 mRNA degradation." (PMID 40744391, 2025). "At low concentrations (<25 μM), DMF activates Nrf2 by modifying KEAP1, promoting antioxidant gene expression and cytoprotection, as seen in breast cancer models where it reduces tumor invasion via macrophage modulation." (PMID 41403438, 2025). "The depletion of KEAP1 in several human breast cancer cell lines leads to the overexpression of several NF-κB controlled genes, including IL-8, involved in tumor angiogenesis." (PMID 39941813, 2025). "We note that KEAP1 is a tumor suppressor gene known to be down-regulated in breast cancer, and KEAP1 promoter methylation is specifically pronounced in ER+ breast cancer patients." (PMID 38862711, 2024). "Given that, this present study provides an in-depth discussion of the important impact of miR-141-3p, an upstream regulator of Keap1-Nrf2 signaling pathway, on paclitaxel resistance in breast cancer cells." (PMID 39308683, 2024). "For example, Keap1 inhibition on the mRNA level has been described to occur in breast cancer following HDACi-dependent upregulation of micoRNAs (e.g., miR-200)." (PMID 39204185, 2024). "miR-141-3p inhibited Keap1 expression, promoted Nrf2 expression, and facilitated paclitaxel resistance in breast cancer cells." (PMID 39308683, 2024). "Targeted inhibition of miR-141-3p significantly promoted ferroptosis by modulating the Keap1-Nrf2 signaling pathway in breast cancer cells under paclitaxel treatment, which in turn inhibited paclitaxel resistance in breast cancer cells." (PMID 39308683, 2024). "Our results showed that overexpression of miR-141-3p inhibited the expression of Keap1 and promoted the expression of Nrf2, as well as significantly promoted paclitaxel resistance in breast cancer cells." (PMID 39308683, 2024).
breast cancer (continued). "miR-141-3p was observed to be overexpressed in breast cancer cells transfected with miR-141-3p mimics, and the mRNA level of its target gene, Keap1, was reduced." (PMID 39308683, 2024). "Subsequently, we overexpressed miR-141-3p in MCF-7 and MDA-MB-231 cells to observe the role of miR-141-3p in the regulation of Keap1-Nrf2 as well as its effect on paclitaxel resistance in breast cancer cells." (PMID 39308683, 2024). "Kitamura and team linked higher IL11 protein levels with Nrf2 expression in human breast cancer and found that Keap1-null MEFs in three-dimensional culture elevate Il11, which crucially impacts tumor engraftment and is reduced by Il11 knockout." (PMID 39286246, 2024). "And, miR-141-3p was experimentally observed to be able to attenuate ferroptosis by regulating the Keap1-Nrf2 signaling pathway, which in turn promoted paclitaxel resistance in breast cancer cells." (PMID 39308683, 2024). "It was further observed that the involvement of DPP3 in NRF2 pathway induction is independent of its enzymatic activity and the interaction of DPP3 and KEAP1 is enhanced by oxidative stress in breast cancer cells." (PMID 37531267, 2023). "MicroRNA 200-a (1p36.22) has been shown to bind to 3′ UTR of KEAP1 mRNA, resulting in decreased KEAP1 mRNA stability, and reduced KEAP1 protein level in two breast cancer cell lines: MDA-MB-231 and Hs578T." (PMID 35268568, 2022). "Here, MCF-7 ER (+) breast cancer cells were used to demonstrate that the DPP3 interaction with KEAP1 was dose-dependently reinforced by increasing the amount of oxidative stressors." (PMID 33805996, 2021). "The other Keap1-Nrf2 disruptor dipeptidyl-peptidase 3 (DPP3) is over-expressed in estrogen receptor-positive breast cancer leading to poor prognosis." (PMID 35126099, 2021). "The oxidative stress-mediated dipeptidyl-peptidase 3 (DPP3) -KEAP1 interaction enhanced the function of NRF2 to promote breast cancer cell survival." (PMID 33292585, 2020). "HBXIP can also act as a modulation factor of cellular oxidative stress by competitively binding KEAP1 to enhance the progression of breast cancer." (PMID 32850453, 2020). "By using miRNA arrays, Eades and coworkers found that forced reexpression of miR-200a, normally repressed in breast cancer cells, was able to impair KEAP1 mRNA translation, inducing NRF2-mediated NQO1 transactivation." (PMID 31097977, 2019). "The KEAP1 promoter hypermethylation was described in neoplastic tissues of patients affected by glioma, breast cancer (51%), and primary NSCLC (47%)." (PMID 29643973, 2018). "Surprisingly, a recent report revealed that NTRK2 inhibits KEAP1 expression in breast cancer cells and is involved in cancer proliferation, survival, and metastasis." (PMID 29306329, 2018). "Inactivating mutations and overexpression of sequestrating proteins of the NRF2 negative regulator KEAP1 have been found in breast cancer, resulting in high protein levels of this transcription factor." (PMID 29290982, 2017). "This 4-OHE2-mediated thiol modification of Keap1 activates Nrf2-HO-1 signaling, which contributes to enhanced proliferation and transformation of mammary epithelial cells, and stimulation of breast cancer cell growth." (PMID 27438141, 2017). "In the context of breast cancer, aberrant Keap1 methylation was found as an independent prognostic factor of better DFS (HR = 0.082), specifically in the patients treated with anthracycline/taxane-based chemotherapy." (PMID 29348788, 2017). "As has been reported in hepatic cells, Atg7 is required for Keap1 degradation in two different model systems: MDA-MB-231 breast cancer cell lines and mouse embryonic fibroblasts." (PMID 24681637, 2014).
breast cancer (continued). "The Nrf2/Keap1 system is dysregulated in lung, head and neck, and breast cancers and this affects cellular proliferation and response to therapy." (PMID 21489257, 2011). "Here, we obtained miR-141-3p by screening miRNAs that are highly expressed in breast cancer with miRNAs that may bind to Keap1." (PMID 39308683, 2024). "On what concerns breast cancer development, lower levels of NRF2 due to polymorphisms in NRF2 or KEAP1 alone or in association with polymorphisms in estrogen biosynthesis and metabolism might contribute to inefficient estrogen detoxification." (PMID 39001473, 2024). "Since Keap1 is a key protein in the regulation of Nrf2, and Nrf2 has an important antioxidant role in cells, we focused on the expressions of Keap1 and Nrf2 after overexpression of miR-141-3p in breast cancer cells." (PMID 39308683, 2024). "Furthermore, the upregulation of Nr2 and downregulation of KEAP1 mediate the unfavorable prognosis in breast cancer." (PMID 39286246, 2024). "Therefore, epigenetic treatment (HDAC inhibitors) can constrain breast cancer cell growth, in part, via activation of the Nrf2-dependent antioxidant pathways, mediated by the re-expression of miR-200a and the targeting of the Keap1 3’-UTR." (PMID 38970040, 2024). "They demonstrated that the combination of Wogonin and radiation therapy effectively suppressed DNA methylation and histone deacetylation in radioresistant breast cancer cells, leading to epigenetic upregulation of CpG site methylation in the Keap1 promoter region." (PMID 38993643, 2024). "For example, miR-200a stimulates the NRF2/KEAP1 signaling by suppressing KEAP1 to decrease ROS concentration in breast cancer cells, while a few identified miRNAs including miR144/153/27a/142-5p directly modulate NRF2 dependent redox homeostasis by suppressing NRF2 gene expression in neuronal cells." (PMID 35754474, 2022). "However, few published studies have shown that the Nrf2 and keap-1 pathways are more highly activated in breast cancer, which has ER, PR, and HER receptor positivity, than in TNBC." (PMID 35571115, 2022). "The promoter hypermethylation of Keap1 that can lead to reduction of Keap1 expression and Nrf2 accumulation in the nucleus has been identified in malignant glioma, lung, prostate, colorectal, gastric and breast cancers." (PMID 35773670, 2022). "Saeidiet al. reported that PIN1 could stabilize and constitutively activate NRF2 by competing with Keap1 for Nrf2 binding in breast cancer." (PMID 35983979, 2022). "Importantly, the NRF2 genetic depletion was significantly abrogated, while its overexpression or KEAP1 knockdown markedly enhanced breast cancer cell proliferation, migration and invasion." (PMID 33805996, 2021). "More in detail, by using MCF-7 and MDA-MB-231 breast cancer cells, the authors showed that the inhibition of NRF2 and overexpression of Kelch-like ECH-associated protein-1 (KEAP1) reduced the expression of G6PD, while NRF2 overexpression or KEAP1 knockdown had the opposite effect." (PMID 33805996, 2021). "In breast cancer cells miR-200a targeted Keap1 to activate Nrf2 signaling cascade." (PMID 32102665, 2020). "In addition, miR-200a was downregulated in breast cancer and re-expression of miR-200a released Nrf2 from Keap1 via triggering Keap1 mRNA degradation, leading to nuclear translocation of Nrf2 and subsequent transcription of target genes." (PMID 35006436, 2020). "In response to oxidative stress, breast cancer cells could upregulate xCT via the KEAP1/NRF2 pathway to antagonize ROS in cells." (PMID 33292585, 2020). "Similarly, a regulatory role of p62 in the NRF2/KEAP1 pathway was also observed in the context of breast carcinoma." (PMID 31097977, 2019). "Recent additional studies in this field gave the first hint of the prognostic role of single-nucleotide polymorphisms (SNPs) of the KEAP1 gene in breast cancer without inducing any evident and detectable variations of the protein structure or conformation." (PMID 29643973, 2018).
breast cancer (continued). "miR-200a regulates NRF2 activation by targeting KEAP1 mRNA in breast cancer cells." (PMID 28523248, 2017). "Cisplatin is a weak inducer of ARE in the MCF-7 human breast cancer cell line (without KEAP1 mutation) and induces a 1.3-fold change in ARE expression levels after 24 h of exposure, consistently with our observations in wild-type KEAP1 NSCLC cells." (PMID 27601007, 2016). "We speculated whether Keap1 played a role in circ‐0100519 promoting breast cancer progression." (PMID 39107958, 2024). "Therefore, focusing on the ability of the Keap1-Nrf2 signaling pathway that exerts intracellular resistance to ferroptosis could help to explore the specific mechanisms which breast cancer cells exhibit chemoresistance." (PMID 39308683, 2024). "Therefore, the targeting of the Nrf2/Keap1/miR-200 axis could be an appropriate choice for breast cancer treatment." (PMID 38970040, 2024). "It is worth mentioning that the NRF2/KEAP1 signaling pathway plays a key role in neurodegenerative diseases, inflammatory therapies, as well as in a variety of cancerous and non-cancerous diseases, such as pre-eclampsia, ovarian cancer, breast cancer, prostate cancer, and traumatic brain injury." (PMID 38138445, 2023). "Aberrant hypermethylation in KEAP1 promoter region was the most common alteration found in nearly half of the non-small cell lung cancer (NSCLC) cases, and has been proven to be associated with poor prognosis in various cancers including malignant glioma, breast cancer and pancreatic cancer." (PMID 35754474, 2022). "In conclusion, the authors confirmed that the genetic variants in the KEAP1 gene were associated with the outcomes of patients with breast cancer and that these SNPs may cause defects in the antioxidant defense mechanisms, underscoring the importance of the NRF2/KEAP1 signaling pathway." (PMID 33805996, 2021). "Analysis of clinical breast cancer samples revealed an inverse correlation between a high expression of CUL3/KEAP1 and IKKβ, while a combination of low KEAP1 and CUL3 expression and high IKKβ expression was a predictor of poor survival." (PMID 39941813, 2025). "Future studies will investigate baicalein’s therapeutic effects on diseases such as breast cancer and sepsis, with a focus on the NRF2/KEAP1 pathway." (PMID 40227198, 2025). "In the spontaneous MMTV-PyMT breast cancer model, where endogenous T-cell activity usually restrains lesion outgrowth on the C57BL/6 background, tumors in conditional Keap1 KO hosts grew rapidly once palpable, whereas >60 % of WT tumors plateaued." (PMID 41176316, 2025). "Wogonin can epigenetically regulate the Keap1 gene, inhibiting the Nrf2/HIF-1α pathway, inducing apoptosis in breast cancer cells, and alleviating acquired radioresistance." (PMID 38993643, 2024). "In MCF-7 human breast cancer cells, the binding of DPP3 with KEAP1 stabilizes KEAP1, thereby allowing Nrf-2 to accumulate and locate in the nucleus and affect prognosis through the regulation of apoptosis." (PMID 38655619, 2024). "The levels of HBXIP that can compete with Nrf-2 for binding with Keap1 protein, via its highly conserved GLNLG motif, are positively correlated with Nrf-2 expression in breast cancer cells and clinical breast cancer tissue samples." (PMID 36701089, 2023). "Breast cancer cells employ HBXIP, which competes with Nrf2 for binding to the Keap1 protein, to activate the Nrf2-ARE pathway." (PMID 35027562, 2022). "A previous report suggests that the expression of Keap1 increased and reduced the expression of Nrf2 in the DMBA-induced breast cancer group rats." (PMID 31556759, 2019). "For example, in breast cancer, miR-28 regulates NRF2 expression through a KEAP1-independent mechanism." (PMID 28523248, 2017). "In a siRNA-mediated transient KEAP1 inhibition approach, AKR1C1, 1C2, 1C3, and other NRF2 target genes were increased in both human keratinocytes and breast cancer cell line." (PMID 23766854, 2013).
breast cancer (continued). "Other interesting observations included the mutual exclusivity of KEAP1 and STK11 in NSCLC and enrichment for CDH1, PIK3CA, and ARID1A along with mutual exclusivity with BRCA1/2, PTEN, and ESR1 in breast cancer." (PMID 40178042, 2025). "As Keap1-Nrf2 plays an important role in cellular resistance to ferroptosis 37, 38, We focused on changes in SLC7A11-GSH-GPX4, an important ferroptosis resistance system, and ferroptosis levels after disrupting miR-141-3p in breast cancer cells." (PMID 39308683, 2024). "The results of our experiments showed that ML385 did not affect the expressions of Keap1 and total Nrf2 (T-Nrf2) in breast cancer cells, but significantly reduced the expression of Nrf2 in the nucleus (N-Nrf2)." (PMID 39308683, 2024). "To ensure that Keap1 stress-induced inclusion formation was not a HeLa cell line-specific phenomenon, we treated two human breast cancer cell lines, 21MT-1 and SKBR3, with 300 μM H2O2 for 3 h and performed immunofluorescence microscopy for endogenous Keap1 expression." (PMID 35204126, 2022). "For example, a previously validated KEAP1 degron in IKBKB71 was lost in HOOK3-IKBKB fusions in breast cancer, but this fusion event did not surpass our stringent false discovery rate cutoff." (PMID 34795215, 2021). "Similarly, the protein dipeptidyl peptidase 3 (DPP3) was shown to inhibit NRF2 ubiquitination through binding to KEAP1, thus activating NRF2-dependent gene transcription in breast cancer." (PMID 33808001, 2021). "Previous studies carried out in vitro have demonstrated induction of PRDXs via the Nrf2/Keap1 pathway, but there are no reports on Nrf2 or Keap1 in clinical breast cancer material." (PMID 21693047, 2011). "Therefore, from a total of 28 breast cancer cases, 16 were successfully genotyped for the three types of tissue (blood, surrounding and tumour tissue) for NRF2 SNPs (rs35652124, rs6706649 and rs6721961) and for rs1048290 of KEAP1." (PMID 39001473, 2024). "In this regard, we aim to evaluate and compare the genotype of these SNPs of KEAP1 (rs1048290) and of NRF2 (rs35652124, rs6721961, rs6706649) in blood, surrounding tissue and tumour tissue, and correlate it with clinicopathological data to evaluate a possible relation with breast cancer prognosis." (PMID 39001473, 2024). "Additionally, MCL has been demonstrated to counteract tamoxifen resistance in breast cancer (BC) by downregulating the expression of Amidohydrolase 1 (ASAH1), adjusting the ROS/AKT signaling pathway, and activating the NRF2/KEAP1 antioxidant mechanism." (PMID 40051564, 2025). "In breast cancer paradoxical connection between Keap1 and worse survival may derive from the sensitive induction of Keap1 in stressed tumors, rather than carcinogenesis promoting features of Keap1 itself." (PMID 25879528, 2015). "It has been reported that in human breast cancer cells, miR-28 degrades the Nrf2 mRNA by binding to its 3’UTR, which is independent of Keap1." (PMID 35006436, 2020). "Similarly, KEAP1 knockdown has varying effects depending on cancer type, for example, it inhibits metastasis in N87 (gastric cancer) and HCC1954 (breast cancer) cells, but enhances metastasis in HCC1806 and MCF7 (breast cancer) cells, with no impact on ZR-75-1 (breast cancer) cells." (PMID 40507333, 2025).